ENSG00000289282 (novel protein)
Gene: Protein-coding gene on chromosome 6 (31,623,874 to 31,625,499, forward strand). Ensembl gene ENSG00000289282.
Genetic constraint (gnomAD): Loss-of-function variants: 3 observed, 27.91 expected, observed/expected ratio (o/e) 0.11, 90% interval 0.048 to 0.28. Missense variants: 122 observed, 184.68 expected, observed/expected ratio (o/e) 0.66, 90% interval 0.57 to 0.77. Synonymous variants: 78 observed, 71.51 expected, observed/expected ratio (o/e) 1.09, 90% interval 0.91 to 1.32.